SPSB1 (splA/ryanodine receptor domain and SOCS box containing 1)
Description:
Substrate recognition component of a SCF-like ECS (Elongin BC-CUL2/5-SOCS-box protein) E3 ubiquitin-protein ligase complex which mediates the ubiquitination and subsequent proteasomal degradation of target proteins. Negatively regulates nitric oxide (NO) production and limits cellular toxicity in activated macrophages by mediating the ubiquitination and proteasomal degradation of NOS2. Acts as a bridge which links NOS2 with the ECS E3 ubiquitin ligase complex components ELOC and CUL5.
Synonyms: SSB-1; SSB1
Tractability: PROTAC: ubiquitination databases record sites on it.
Gene: Protein-coding gene on chromosome 1 (9,292,101 to 9,369,532, forward strand). Ensembl gene ENSG00000171621.
Subcellular location: Cytoplasm; Cytoplasm, cytosol
Pathways (Reactome):
Immune System: Antigen processing: Ubiquitination & Proteasome degradation
Metabolism of proteins: Neddylation
Gene Ontology:
Molecular function: protein binding; ubiquitin-like ligase-substrate adaptor activity
Biological process: protein ubiquitination; ubiquitin-dependent protein catabolic process; proteasome-mediated ubiquitin-dependent protein catabolic process
Cellular component: cytosol; SCF ubiquitin ligase complex; cytoplasm
Genetic constraint (gnomAD): Loss-of-function variants: 8 observed, 22.49 expected, observed/expected ratio (o/e) 0.36, 90% interval 0.21 to 0.64. The upper end of that interval is the gene's LOEUF score, 0.64, which puts it in group 2 of 6, group 1 being the genes least tolerant of losing a copy. Missense variants: 242 observed, 389.37 expected, observed/expected ratio (o/e) 0.62, 90% interval 0.56 to 0.69. Synonymous variants: 169 observed, 168.28 expected, observed/expected ratio (o/e) 1, 90% interval 0.88 to 1.14.
Homologues: Orthologues: chimpanzee SPSB1 (99% identical), macaque SPSB1 (99% identical), pig SPSB1 (99% identical), dog SPSB1 (99% identical), guinea pig SPSB1 (99% identical), mouse Spsb1 (99% identical), rat Spsb1 (98% identical), rabbit SPSB1 (97% identical), zebrafish spsb1 (87% identical), tropical clawed frog SPSB1 (82% identical), Drosophila melanogaster gus (71% identical), Caenorhabditis elegans spsb-1 (50% identical), and 1 more. Paralogues in human: SPSB4 (75% identical), SPSB2 (50% identical), FBXO45 (31% identical), SPSB3 (26% identical).
Diseases named in the same sentence as SPSB1 in open-access papers:
SPSB1 is named in the same sentence as 14 diseases in open-access papers, as found by Europe PMC text mining. Sharing a sentence is not in itself a finding about the gene and the disease. The quoted sentences say what the papers report.
Sepsis (2 papers, 2023 to 2025). Sepsis is defined as life-threatening organ dysfunction caused by a dysregulated host response to infection. "In contrast, membranous TβRII‐staining was reduced in myofibers of CLP mice suggesting an association between increased Spsb1 expression and a decrease in its putative target TβRII in myofibers during sepsis." (PMID 37209006, 2023). "Sepsis caused a reduction in body (control_shRNA: −23%, P < 0.001; Spsb1_shRNA: −9%, P = 0.3), TA (−26%, P < 0.01) and GP (−21%, P < 0.01) weights, which was reduced by Spsb1 knockdown." (PMID 37209006, 2023). "Copper accumulation also activates the NF-κB pathway, which induces an increase in SPRY domain-containing SOCS box protein 1 (SPSB1) and has been found to lead to muscle atrophy and weakness in mice with sepsis." (PMID 40182687, 2025). "In our short‐term sepsis mouse model, we observed a 20‐ to 34‐fold increase in muscular Spsb1 expression 24 and 96 h after surgery, respectively." (PMID 37209006, 2023). "Because fast twitch/type‐II myofibers show the strongest atrophy response in sepsis, we analysed if these fibres contain higher amounts of SPSB1." (PMID 37209006, 2023). "Spsb1 knockdown attenuated sepsis‐induced increases in Trim63 and Fbxo32 expression." (PMID 37209006, 2023). "An increased expression of SPSB1 could therefore be beneficial to limit TGF‐β‐induced inflammation in sepsis." (PMID 37209006, 2023). "Besides the atrophy markers Trim63/MuRF1, Fbxo32/Atrogin‐1, and Fbxo30/MuSA1 (all induced >5‐fold by sepsis, P < 0.001) the expression of Spsb1 was significantly increased after 24 and 96 h of sepsis (24 h: 20‐fold; 96 h: 34‐fold, P < 0.001)." (PMID 37209006, 2023). "The inhibition of TGF‐β/TβRII‐Akt‐Myogenin signalling by SPSB1 may shed light on the pathogenesis of the perturbed regenerative capacity observed in muscle of critically ill patients with sepsis." (PMID 37209006, 2023). "However, if SPSB1 also inhibits anti‐inflammatory TGF‐β‐functions in muscle during sepsis warrants further investigation." (PMID 37209006, 2023). "The proposed model that inflammatory cytokines induce SPSB1 to block TGF‐β signalling and myogenesis could also be interpreted as a lifesaving mechanism during the early stages of sepsis, which may result in failed regeneration during the later disease course." (PMID 37209006, 2023). "In this regard, the cytokine‐mediated increase in SPSB1 could inhibit TGF‐β‐induced protein synthesis, satellite cell proliferation and muscle repair to prioritize defence mechanisms in sepsis." (PMID 37209006, 2023). "Third, unlike Spsb1 the other SPSB‐family members were either only regulated in some muscles, at different time points or not regulated during sepsis in mice." (PMID 37209006, 2023).
aortic aneurysm (1 paper, 2025). A ruptured aneurysm located in the wall of the proximal portion of the descending aorta proceeding from the arch of the aorta. "As aged SMCs are known to accumulate in aortic aneurysms, we further investigated the role of SPSB1 in SMC senescence." (PMID 41251448, 2025).
ascending aortic aneurysm (1 paper, 2025). "To further investigate SPSB1 expression, we analyzed two mouse models of thoracic aortic pathology: the BAPN‐induced model and the transverse aortic constriction (TAC) model, the latter representing a pressure‐overload‐induced ascending aortic aneurysm." (PMID 41251448, 2025).
neuroblastoma (1 paper, 2023). Neuroblastoma (NB) is the most common solid, extracranial childhood tumor. "Importantly, TGF‐β signalling can be inhibited by the splA/ryanodine receptor (SPRY) domain and SOCS‐box domain 1 (SPSB1/Spsb1) protein that targets TβRII for UPS‐dependent degradation in neuroblastoma cells." (PMID 37209006, 2023).
viral infection (1 paper, 2019). "Here we present the novel finding that a member of the CRL5 family, SPSB1, downregulates the expression of inflammatory cytokines and other NF-κB-dependent genes in airway epithelial cells exposed to cytokines and viral infection." (PMID 32038638, 2019).
cancer (5 papers, 2016 to 2024). A tumor composed of atypical neoplastic, often pleomorphic cells that invade other tissues. "SPSB1 is known to target the inducible nitric oxide synthase (iNOS) and has been linked with several pathways related to cancer, but no direct role for SPSB1 in controlling NF-κB activation has been reported." (PMID 32038638, 2019). "In contrast, we identified that genes splA/Ryanodine receptor domain and SOCS box containing 1 (SPSB1) and proteasome 20S subunit alpha 8 (PSMA8) are frequently subjected to low CNV in numerous cancer types." (PMID 38794205, 2024). "It is noteworthy that we observed 3′LTR-driven antisense-dependent chimeric transcripts involving well-established cancer drivers located upstream of the provirus in the 11 ATLs with 5′LTR-deleted defective HTLV-1 proviruses (i.e., SPSB1)." (PMID 28534499, 2017). "Genes positively correlated with purity showed enrichment in cancer-related pathways and processes such as epithelial-mesenchymal transition (BASP1, COL4A1, THBS2), genes involved in the TNFA signaling via NFKB (SPSB1, SMAD3), and genes upregulated by KRAS activation (CFB, MAFB)." (PMID 37041233, 2023).
tumor (4 papers, 2019 to 2022). "In the case of SPSB1, we discovered that the germline mutation (p.R202W) was deleted in the tumor genome and thus the remaining allele was wildtype." (PMID 35725745, 2022). "A study shows that lincRNA-p21 acts as a tumor suppressor and SPSB1 destabilizes p21WAF1/Cip1." (PMID 31900225, 2020).
cardiovascular disease (1 paper, 2015). "Findings related to cardiovascular disease and inflammation (MAP3K7 and SPSB1) could be tied to fenofibrate response, other findings are more difficult to link to the drug's mechanism (e.g., AGO1)." (PMID 26483836, 2015).
infection (1 paper, 2019). The state of being infected such as from the introduction of a foreign agent such as serum, vaccine, antigenic substance or organism. "SPSB1, SPSB2, and SPSB4 can interact with inducible nitric oxide synthase (iNOS) resulting in its proteasomal degradation to regulate the host’s response to infection." (PMID 31344133, 2019).
myopathy (1 paper, 2023). A disease of the muscle in which the muscle fibers do not function properly. "Our mechanistical data on the role of SPSB1 in myogenic differentiation suggest the TβRII‐Akt‐Myogenin pathway contributes to defective muscle regeneration and myopathy observed in ICUAW patients." (PMID 37209006, 2023).
SPSB1 also shares sentences with these, for which no sentence is quoted: breast carcinoma (1 paper); colon cancer (1); mild cognitive impairment (1); venous thromboembolism (1).